TET2 (tet methylcytosine dioxygenase 2)
Diseases named in the same sentence as TET2 in open-access papers (continued):
Sharing a sentence is not in itself a finding about the gene and the disease.
acute myeloid leukemia (continued). "TET2 mutations are common in haematological neoplasms and can occur in 30% of myelodysplastic syndrome (MDS), 20% of myeloproliferative neoplasms (MPNs), 30% of secondary acute myeloid leukemia (sAML), 17% of novel AML, and 50–60% of chronic myelomonocytic leukemia (CMML) cases." (PMID 35279121, 2022). "Following studies provided further evidence regarding the incidental and non-malignant significance of the persistence of DNMT3A, TET2 and ASXL1 mutations detectable by NGS after initial induction chemotherapy for acute myeloid leukemia (AML)." (PMID 33562056, 2021). "Concordantly, several TF were reported to interact with TET2, including Wilms Tumor 1 (WT1), which was found to recruit TET2 to its target genes in acute myeloid leukemia (AML) cells, or early B-cell factor 1 (EBF1), which was reported to interact with TET2 in IDH-mutant cancers." (PMID 33692344, 2021). "Interestingly, genetic alterations commonly found in acute myeloid leukemia like DNMT3, TET2, NPM1, IDH1 or IDH2 are rarely detected, suggesting that PML-RARA exhibits a distinct transformation pathway among AML." (PMID 32295268, 2020). "Catalytic mutations in TET2, but not TET1, are commonly identified in patients with hematopoietic disorders and malignancies such as myelodysplastic syndrome, myeloproliferative neoplasms, acute myelogenous leukemia, chronic myelomonocytic leukemia, and B-cell and T-cell lymphomas." (PMID 24958354, 2014). "Somatic mutations in genes such as NPM1, which is involved in the maintenance of HSCs’ quiescence and self-renewal, and TET2, DNMT3A, involved in mediating HSCs’ differentiation, results in the transformation of HSCs thereby leading to the development of Acute Myeloid Leukemia (AML)." (PMID 38571491, 2024). "Non-driver mutations, such as those in ASXL1, EZH2, TET2, SRSF2, and IDH1/IDH2, have been found to exacerbate disease severity, accelerate progression, and increase the risk of transformation to acute myeloid leukemia (AML)." (PMID 39434124, 2024). "Similarly, TET2 promoter methylation is not affected in infant ALL, whereas it is clearly hypermethylated in acute myeloid leukemia (AML) patients." (PMID 33803872, 2021).
myeloid malignancies (177 papers, 2010 to 2026). "TET2 mutations frequently occur in the hematopoietic and immune systems, leading to myelodysplasia and related myeloid malignancies 178, and approximately 15% of myeloid cancers harbor somatic TET2 mutations." (PMID 40093905, 2025). "Loss-of-function mutations in TET2 were frequently observed in myeloid malignancies and resulted in decreased 5hmC levels, increased 5mC levels, and impaired hematopoietic differentiation." (PMID 41516186, 2025). "Among the various genetic alterations implicated in AML, ten-eleven translocation 2 (TET2) mutations have garnered attention due to its high prevalence in myeloid malignancies and its impact on DNA demethylation and epigenetic regulation." (PMID 41561754, 2025). "Of note, TET2, IDH2 and DNMT3A mutations are recurrent in myeloid malignancies, while TET2 and DNMT3A mutations are described in clonal haematopoiesis of indeterminate potential." (PMID 40724970, 2025). "One of the most frequently mutated genes in CH and myeloid malignancies is Ten-Eleven Translocation-2 (TET2), an epigenetic enzyme that regulates DNA demethylation and gene activation associated with myeloid cell differentiation." (PMID 40909656, 2025). "In conclusion, the majority of myeloid neoplasm-associated gene variants in AA patients affected TET2, ASXL1 and MPL, and epigenetic- and signal transduction pathway-related genes were the most commonly involved." (PMID 41477271, 2025). "Like DNMT3A, TET2 mutations are associated with an adverse clinical outcome in a context-dependent manner in various myeloid neoplasms." (PMID 40374809, 2025). "Especially, loss-of-function mutations in DNMT3A and TET2 are prevalent in clonal hematopoiesis and myeloid neoplasms, including MDS." (PMID 40929300, 2025). "This is not an isolated case; DNA methyltransferase DNMT3A and demethylase TET2 are both tumor suppressor genes in myeloid tumors, and their mutations are closely related to the occurrence of myeloid tumors." (PMID 40171845, 2025). "TET2 is also a downstream target of other mutated genes that mediate the development of myeloid malignancies." (PMID 40599235, 2025). "Deficiency of Tet2 originates aberrant self-renewal of hematopoietic stem cells and subsequent onset of myeloid malignancies in mice, implying Tet2 functions as a tumor suppressor." (PMID 40473594, 2025). "Our literature analysis underscores the pivotal role of TET2 mutations as a common genetic driver in the pathogenesis of BPDCN arising from myeloid neoplasms." (PMID 41451201, 2025). "TET2 remains the most frequently mutated or deleted TET member in a variety of hematological malignancies, and approximately 15% of individuals with myeloid malignancies harbor a mutation or deficiency in TET2, which correlates with disease progression." (PMID 40663150, 2025). "Our study indicated that MDS/MPN is characterized by mutations commonly identified in myeloid neoplasms, with TET2 (52%) being the most frequently mutated gene, followed by ASXL1 (38.7%), SRSF2 (34.7%), and JAK2 (19.7%), among others." (PMID 39337700, 2024). "TET2-mutated myeloid malignancies tend to have more mutational events than the TET2 wild-type malignancies suggesting that loss of TET2 causes hypermutagenicity." (PMID 38696033, 2024). "Some investigations reported the co-occurrence of ASXL1 mutations with EZH2, IDH1/2, RUNX1, and TET2 in myeloid malignancies." (PMID 38807730, 2024). "The mutations in DMT3A or TET2 - two most common epigenetic alterations observed in age-related clonal hematopoiesis and myeloid malignancies – initiate the proinflammatory state." (PMID 38440231, 2024). "Our results demonstrated that MDS/MPN is characterized by the presence of mutations commonly identified in myeloid neoplasms, such as TET2, ASXL1, SRSF2, and SF3B1." (PMID 39337700, 2024).
myeloid malignancies (continued). "As previously reported, a high frequency of gene mutation was identified in lymphoid and myeloid tumours, and approximately 67% of these mutations were located in the catalytic domain, affecting the DNA demethylation activity of TET2." (PMID 37620362, 2023). "This raises the question of the requirement of other mutated genes, in addition to TET2, in order to induce malignant hemopathies and how these mutation profiles can be specific to lymphoid or myeloid malignancies." (PMID 36737440, 2023). "To clarify the mechanisms through which the loss of tet2 contributes to myeloid malignancies using an in vivo animal model, we created a stable zebrafish line with loss-of-function mutations in the tet2 gene generated through zinc finger nuclease technology." (PMID 37937078, 2023). "Somatic mutations of TET2 are frequent and usually occur as early clonal events in patients with myeloid neoplasms, especially CMML." (PMID 36409328, 2023). "Mutation of ten-eleven translocation 2 (TET2), an epigenetic regulator in haematopoietic stem and progenitor cells (HSPCs) is often observed in myeloid malignancies and results in increased self-renewal and myeloid proliferation in patients." (PMID 37808081, 2023). "Loss-of-function mutations in TET2 were first identified in myeloid malignancies but soon thereafter recurrent somatic mutations in TET2 were recognized in approximately 50-70% of AITL and other TFH-derived lymphomas." (PMID 37841428, 2023). "This behavioral change in clonal macrophages aligns with other reports that identified macrophages with TET2 mutations, frequently found in myeloid neoplasms, to drive aberrant inflammation in vivo by releasing inflammatory cytokines." (PMID 37095207, 2023). "The type and frequency of TET2 mutations in BPDCN appear similar to those observed in other myeloid neoplasms." (PMID 36819168, 2023). "In this case series, 4 of 22 patients with TET2 mutations and available sequencing data developed myeloid neoplasms approximately 2-4 years following their lymphoma diagnosis." (PMID 37841428, 2023). "TET2 was first described as a tumor suppressor in myeloid neoplasms, but afterward, a high loss of function in TET2 was identified in PTCL and especially AITL." (PMID 38023160, 2023). "TET2 mutations are prevalent in a range of myeloid malignancies, including AML (~23%), MDS (~25%), MPN (~13%), and CMML (~50%), and also in lymphoid malignancies, including T cell lymphoma (~11.9%) and B cell lymphoma (~2%)." (PMID 36675240, 2023). "The myeloid neoplasms all shared multiple TET2 mutations in the myeloid clone and AITL cells but also contained additional different mutations that were not shared." (PMID 37841428, 2023). "Together these data support myeloid neoplasms arising from early clonal TET2-mutated hematopoietic stem cells but with divergent evolution from the neoplastic AITL cells." (PMID 37841428, 2023). "Single-cell transcriptomic profiling of hematopoietic stem and progenitor cells into differentiated monocytes was analyzed in an animal model carrying a recurrent TET2 missense mutation who developed a wide range of myeloid neoplasms late in life." (PMID 36830713, 2023). "The DNA demethylating enzyme TET2, essential for hematopoietic stem cell differentiation and lineage commitment, is frequently mutated in myeloid malignancies." (PMID 35085104, 2022). "DNA hydroxymethylation is catalyzed by the TET protein family member, with TET2 being one of the most frequently mutated genes in patients with myeloid neoplasms." (PMID 35765052, 2022). "TET2 is one of the most frequently mutated genes in myeloid neoplasms, including MDS and chronic myelomonocytic leukemia, and is a negative prognostic factor." (PMID 35956220, 2022).
myeloid malignancies (continued). "The myeloid neoplasms with del(9q) were identified as having a high prevalence of TET2 mutations, and the association was more pronounced when TET2 was the sole abnormality, with a frequency of 45%." (PMID 35885487, 2022). "TET2 mutations are predominantly insertions and deletions generating frameshift and nonsense mutations, similar to those found in myeloid neoplasms." (PMID 35330161, 2022). "Somatic mutations in TET2 occur in about 15–30% of patients with various sporadic myeloid malignancies." (PMID 35884491, 2022). "TET2 is a member of the TET family of proteins with mutations of this gene occurring in 15% of myeloid malignancies." (PMID 34065087, 2021). "Compared with other myeloid malignancies, the prevalence of TET2 gene mutations among patients with BCR-ABL-negative MPN appears to be lower." (PMID 34203097, 2021). "Somatic TET2 mutations are commonly found in myeloid malignancies (MN) at frequencies varying according to disease subtypes." (PMID 33808599, 2021). "Much controversy has been elicited regarding the prognosis of myeloid malignancies with TET2 mutations." (PMID 34660059, 2021). "TET2 encodes a methylcytosine dioxygenase that was shown to be involved in DNA demethylation, and it is frequently mutated in myeloid malignancies and other disorders." (PMID 34249685, 2021). "For the development of myeloid neoplasms, additional mutations beyond CH-associated TET2 and DNMT3A mutations drive further clonal expansion from CH." (PMID 34581268, 2021). "TET2 is the most frequently mutated gene in MDS, and biallelic TET2 gene inactivation is frequently observed in myeloid neoplasms." (PMID 34203454, 2021). "Mutations in the epigenetic modifier TET2 are frequent in myeloid malignancies and clonal hematopoiesis of indeterminate potential (CHIP) and clonal cytopenia of undetermined significance (CCUS)." (PMID 34663818, 2021). "In myeloid malignancies, the expression of the Tet2 gene and its variants was first identified in 2009." (PMID 34222235, 2021). "Several studies suggest that TET2 mutations are an early event in the development of myeloid malignancies, yet their function in normal cells and pathologic conditions remains to be elucidated." (PMID 34660059, 2021). "DNMT3A mutation was shown to be associated with response to decitabine and azacytidine therapy in myeloid malignancies, and TET2 mutation was associated with the objective response to these DNMT inhibitors in MDS." (PMID 34039392, 2021). "Using this methodology, we found that the best predictor/marker of TET2 mutations in patients with myeloid malignances (MDS) was 5fC." (PMID 33921666, 2021). "Recently, TET2 has been considered as a novel tumor suppressor, and TET2 mutations have been demonstrated to be acquired in 12–24% of myeloid neoplasms, including AML, MDS, CMML and MPN19." (PMID 32066746, 2020). "In myeloid neoplasms, TET2 and IDH1/2 mutations are usually mutually exclusive, but they are often paired together in Angioimmunoblastic T-cell Lymphoma (AITL)." (PMID 33520997, 2020). "TET2 is one of the most frequently mutated genes in myeloid malignancies, resulting in a dysregulated DNA methylation pattern in malignant cells." (PMID 32726753, 2020). "Hematopoietic progenitor cells from mice deficient for Tet methylcytosine dioxygenase 2 (TET2), a gene frequently mutated in patients with myeloid malignancies, show enhanced self-renewal potential and an increased myeloid lineage bias." (PMID 32849521, 2020). "TET2 is widely affected by mutations in myeloid neoplasms, and is one of the most commonly mutated genes in CHIP." (PMID 31963585, 2020). "Most importantly, loss of function of Tet2 in mice results in abnormal DNA hydroxymethylation patterns in bone marrow cells and leads to the emergence of myeloid malignancies between 2 and 4 months of age." (PMID 33537318, 2020). "Overall, somatic mutations in TET2 have been found to occur in approximately 15% of patients with myeloid malignancies." (PMID 31963585, 2020).
myeloid malignancies (continued). "Several studies have assessed the structure of the TET2 protein and the context of somatic mutations in myeloid malignancies, including the domains in which they occur." (PMID 31963585, 2020). "In 2009, expression of the Ten-Eleven Translocation-2 (TET2) gene and its variants was demonstrated in myeloid malignancies." (PMID 31001476, 2019). "TET2 mutations frequently occur in myeloid malignancies and are accompanied by a decline in 5-hmC and poor prognosis." (PMID 31151404, 2019). "TET2 is a master regulator of normal hematopoiesis, and mutations of the TET2 gene have been frequently identified in multiple spectra of myeloid malignancies." (PMID 29069286, 2018). "Mutations in TET2 gene were first identified in myeloid neoplasm, and they have been reported in 19-26% of MDS cases and 50% of CMML cases." (PMID 28476038, 2017). "TET2 mutations are a common event in a spectrum of myeloid malignancies and are one of the most frequent gene mutations in MDS and CMML." (PMID 28476038, 2017). "TET2 overexpression in KI mice was shown to induce B cell reprogramming, while the loss of TET2 induces myeloid malignancies such as chronic myelomonocytic leukemia in KO mice." (PMID 29029465, 2017). "Although TET2 deletions and loss-of-function mutations are more frequent in myeloid malignancies, they were observed in approximately 2% of various B cell malignancies, including a total 5.7% of patients diagnosed with diffuse large B cell lymphoma." (PMID 28408905, 2017). "For this purpose, TET2 mutation analysis and TET2 gene expression were tested by Sanger sequencing and quantitative PCR, respectively, in bone marrow samples from healthy donors and myeloid neoplasm patients." (PMID 26984174, 2016). "New sequencing technologies have enabled the identification of mutations in Ten-eleven-translocation 2 (TET2), an enzyme that catalyzes the conversion of 5-methylcytosine into 5-hydroxymethylcytosine (5-hmC) in myeloid neoplasms." (PMID 26984174, 2016). "The detailed mechanism of how TET2 mutations propagate leukemic and pre-leukemic states in myeloid malignancies remains poorly understood." (PMID 27597933, 2016). "We herein aimed to investigate TET2 mutations and their impact on TET2 expression in a cohort of patients with myeloid neoplasms, including MDS and AML patients." (PMID 26984174, 2016). "TET2 mutations in exons have been implicated in protein loss-of-function and myeloid neoplasm mechanism of disease, which supports our focus on sequencing TET2 coding regions only." (PMID 26984174, 2016). "In myeloid malignancies, TET2 mutations are associated with a decrease in 5-hmC levels and an increase in 5-mC levels with respect to TET2-wild-type samples." (PMID 25632305, 2015). "Delhommeau and colleages then sequenced TET2 in patient tumor samples, becoming the first group to identify TET2 mutations in multiple myeloid neoplasms, including MDS (19%), MPNs (12%–14%), and sAML (24%)." (PMID 24622842, 2014). "Likewise, mutations at 19 residues in TET2 are reported at least twice in solid human cancers, which are also reported in myeloid malignancies, with mutations at residues 29, 550, 1516, 1718, and 1762 occurring most frequently in solid tumors." (PMID 40116537, 2025). "This suggests that in the setting of Tet2 loss-of-function, inflammatory signaling may be associated with the development of myeloid malignancies." (PMID 39626264, 2025). "Routine examination of pDCs in myeloid malignancies, particularly those harboring TET2 mutations, may be essential for elucidating the mechanisms underlying BPDCN development and its clonal evolution." (PMID 41451201, 2025). "This study also established a correlation between TET2 status and myeloid malignancy‐related death, with approximately 33% (21/62) of TET2−/− mice dying before 1 year of age with death directly linked to myeloid malignancy, compared to only 8% (5/66) of TET2+/− mice." (PMID 40116537, 2025).